SPHK1 (sphingosine kinase 1)
Diseases named in the same sentence as SPHK1 in open-access papers (continued):
Sharing a sentence is not in itself a finding about the gene and the disease.
cancer (continued). "Despite successful anti-SphK1 inhibitor studies in vitro, these compounds have not yet been translated into drugs for cancer treatment." (PMID 28869494, 2017). "On the contrary, the high activity of sphingosine kinase-1 but no ceramide generation during anti-cancer treatment has been shown in chemo-resistant HL-60 cells." (PMID 29216917, 2017). "Non-oncogenic addiction refers to the over reliance of cancer cells on the SphK1 signaling pathway for survival." (PMID 28415564, 2017). "As discussed in this review, cancer cells can become dependent on the SphK1 enzyme for survival and proliferation, termed non-oncogenic addiction." (PMID 28415564, 2017). "It is known that TNF-α can activate SPHK1 in endothelial cells promoting anti-apoptotic effect; thus, TNF-α may be a trigger of the S1P pathway, mainly by activating SPHK1, favoring the cancer development." (PMID 29186783, 2017). "First, we examined whether SphK1 and COX-2 are overexpressed in cancer tissues as compared to adjacent normal tissues." (PMID 28583134, 2017). "In this regard, development of a pharmacological inhibition therapy targeting SphK1 is a useful therapeutic strategy for both early and late stages of cancer, although no specific inhibitors targeting SphK1 have been developed as yet57." (PMID 26877098, 2016). "Finally, regulation of SphK1 expression and S1P secretion by ECM stiffness is dependent on cancer cell origin." (PMID 26877098, 2016). "Furthermore, the activity and expression of SPHK-1 are significantly induced under hypoxia and by HIF-1α, and thus is a critical therapeutic target through pVHL-dependent proteasomal degradation for cancer treatment." (PMID 27581969, 2016). "Nevertheless our data demonstrates that S1P production controlled by SPHK1 and SGPL1 are key determinants of cytotoxic drug resistance and that decreasing S1P production in cancer cells could lead to increased cytotoxic sensitivity." (PMID 26493335, 2015). "Recently, it was discovered that fingolimod inhibited sphingosine kinase 1 (SK1), which may be relevant to cancer progression." (PMID 25756279, 2015). "The oncogenic role of SphK1 has been extensively studied in CRC and other cancers." (PMID 26337959, 2015). "Sphingosine kinase 1 (SK1) is an oncogenic enzyme that is highly expressed in human tumours and has been shown to act as a `signalling hub’ mediating cancer progression, angiogenesis and cell migration, making it a key molecule in the search for potential anticancer therapies." (PMID 25482303, 2014). "SPHK1-S1P receptor signalling activates the ERK1/2 pathway, a well-established driver of cell proliferation and survival that is constitutively activated in many forms of cancer." (PMID 24970218, 2014). "Our results imply that SPHK1 may be the central controller of amplification loops of EGF, AREG and EREG-EGFR interactions that can contribute to cancer progression." (PMID 21936950, 2011). "Studies on SPHK1 inhibitors have made some progress, while no ideal SPHK1 inhibitor is currently used for treating cancer in the clinic, and there are also other compounds including S1PR1 and S1PR3 (VPC03090) or S1PR2 (AB1) antagonists under preclinical evaluation." (PMID 36361531, 2022). "Additionally, in the case of SphK1 staining, in two cases the staining was negative both in cancer and closely connected healthy tissue." (PMID 35806446, 2022). "Furthermore, since SPHK1 and peroxisome proliferator-activated receptor-γ (PPARγ) are known to be expressed in human cancers, PPARγ was reported as a transcription factor target for S1P generated by SPHK1, independent of the S1P receptors." (PMID 35565311, 2022). "Similarly, it is expected that both SPHK1 and SPHK2 would provide cancer resistance in humans." (PMID 35004331, 2021). "Moreover, and contrary to depletion experiments, use of the SPHK1 selective inhibitor PF-543 fails to induce cell death in different cancer cell lines." (PMID 34033645, 2021).
cancer (continued). "Hypoxia also upregulated Sphk1 mRNA expression in endothelial cells and cancer cells, and this was mediated by the transcription factors HIF-1α and HIF-2α, which can bind to one of the two hypoxia response elements (HREs) identified in the human Sphk1 promoter region." (PMID 34502385, 2021). "In view of the absence of SPHK1 mutations across various cancer types, it is suggested that tumors exhibit a dependency on hyperactivation of SPHK signaling that confers survival and growth advantages to cancer cells, a phenomenon known as “non-oncogenic addiction”." (PMID 34820423, 2021). "Therefore, SPHK1 and S1P may serve as promising therapeutic targets to alleviate EMT-mediated metastasis by disrupting sphingolipid metabolism in cancers." (PMID 32509584, 2020). "Thus, given the known role of Sphk1 in other cancers but not in HCC, we proposed that this pathway needed to be specifically examined in HCC." (PMID 29643998, 2018). "Nevertheless, SphK1 overexpression is not an indicator for all cancers." (PMID 28415564, 2017). "Interestingly, the inhibition of SphK1 in various carcinoma cells (breast, lung and colon) decreased proliferation and cell survival by compromising PKC activity and cytokinesis, which suggests a central PKC-dependent role of S1P in these carcinoma cells." (PMID 29149079, 2017). "To substantiate that inhibition of the SphK1/S1P pathway could represent a pertinent idea, we evaluated the relevance of inhibiting the extracellular S1P signaling with regard to HIF-1α accumulation under hypoxia in cancer cells." (PMID 25915662, 2015). "The lack of effect of these recently developed inhibitors on cancer cell proliferation and survival sits in contrast to studies with earlier generation inhibitors, such as the dual SPHK1/2 inhibitors dimethylsphingosine and SKI-II, and the SPHK1-selective inhibitor SK1-I." (PMID 24970218, 2014). "We found that LRRC15, ITGA11 and SPHK1 were also specifically expressed on CSFs, but not in other clusters of fibroblasts, indicating that they could also be attractive CSFs specific targets for cancer treatment." (PMID 36744260, 2023). "While SPHK1 was not a network hub, it was among the top-bottleneck proteins indicating it be a highly ‘between’ among small network clusters and thus could possibly play important roles in mediating signaling during cancer progression." (PMID 36309544, 2022). "In their mouse model, SphK1−/−/KO, HNSCC was significantly reduced, and they speculated that SphK1 activation was required to induce proinflammatory cytokines (including the interleukins IL-1b and IL-6) in the mediation of inflammation-related HNSCC cancer development." (PMID 35158806, 2022). "Additionally, ISO treatment lowered the expression of SPHK1/2 and polymerized tubulin supporting the fact that inhibition of the SPHKs and tubulin polymerization could be a reason behind the anti-cancer effect of ISO against TNBC and non-TNBC cell lines." (PMID 31817453, 2019). "Therefore, SPHK1 and SPHK2, as well as S1P itself, have been recognized as promising targets for cancer treatment, and many SPHK inhibitors, either selective or non-selective for SPHK1 and SPHK2, have been developed, some of which are now being used in clinical trials." (PMID 29208982, 2017). "Although there are no current studies exploring the expression of SphK specific isoforms in cancer patients, these initial in vitro studies in cancer cell lines, suggest that differences in SphK1 isoform expression may be relevant in anti-SphK/S1P/S1PR cancer based therapies." (PMID 28869494, 2017). "In addition, FTY720 could act as a SphK1 inhibitor to exhibit the antiproliferative effect in various cancers in a manner independent of S1P receptors." (PMID 26673009, 2016).
cancer (continued). "However, recent studies show that highly potent and selective SPHK1 inhibitors do not affect cancer cell proliferation or survival thus raising the possibility that regulation through sphingosine itself might play a more important role in oncogenic transformation and tumor growth." (PMID 29643998, 2018). "Previously we reported that S1P produced by SPHK1, but not SPHK2, is a critical mediator of cancer-induced lymphangiogenesis." (PMID 30018456, 2018). "S1P produced by SPHK1, not SPHK2, is exported out of cancer cells through transporters, and act in paracrine and autocrine manner, which is known as “inside-out signaling”12." (PMID 30018456, 2018). "We have found that plasma S1P is secreted from RBCs and is decreased during the early PCa progression, which reflects a functional change in the RBCs SphK1 activity and not RBC counts in response to cancer presence." (PMID 22315056, 2012). "The anti-cancer activity of FTY720 could be ascribed to the induction of protein phosphatase 2A (PP2A) activity and inhibition or degradation of sphingosine kinase 1, which is not dependent on FTY720 phosphorylation." (PMID 32456134, 2020). "It has been reported that main enzyme that produces S1P is SPHK1, not SPHK2 in cancer cells." (PMID 30018456, 2018). "As opposed to its immunosuppressant activities, the anti-cancer properties of FTY720 are known to be mainly mediated by its non-phosphorylated form, via inhibition of sphingosine kinase 1 (SphK1) and activation of the protein phosphatase 2A (PP2A), leading to the reduction in cell survival." (PMID 28298211, 2017). "This significant change of SphK1 activity was not reflected by lower RBC counts in both PCa patients and healthy controls, indicating that cancer presence may modify erythrocyte cell SphK1 activity irrespective of erythrocyte numbers." (PMID 22315056, 2012). "TCGA data confirmed that CXCL12 and SPHK1 expression correlated in COAD tumor samples, but not in normal colon tissue, suggesting that ramping up CXCL12 and S1P production by cancer cells in the tumor microenvironment may be one strategy used by cancer cells for tumor progression." (PMID 40155684, 2025).
tumor (293 papers, 2006 to 2026). "Considering KMplot microarray data encapsulates all areas of the tumour, including tumour‐associated stroma and tumour epithelium, we assessed SPHK1 protein levels further in a TMA cohort." (PMID 40356021, 2025). "SphK1/S1P signalling has also been linked to the regulation of HIF‐2α expression, which can drive aggressive tumours; therefore, knockdown of SphK1/S1P is associated with lower HIF‐2α protein expression." (PMID 39660488, 2024). "The sphingolipid metabolism pathway was associated with tumor stemness and SPHK1 was found to play an important role in promoting stemness and malignant behaviors in PDAC-TRC." (PMID 37999228, 2023). "Overexpression of CERK and SPHK1 was associated with nodal metastasis, late tumor stage and high proliferation potency." (PMID 36309544, 2022). "Next, we investigated if SPHK1‐packaged EVs cause immune suppression along with increased tumor growth and metastasis in vivo." (PMID 35289120, 2022). "Herein, we elucidated the molecular mechanism underlying how SPHK1 transcriptionally regulates tumor PD-L1 expression." (PMID 36050478, 2022). "Being a S1P transporter, the levels of SPNS2 were found to be positively associated with SPHK1 expression in tumor tissue in the current study." (PMID 36309544, 2022). "High SPHK1 levels were associated with complete tumor resection (p = 0.002 and lower FIGO stage (p = 0.04)." (PMID 33660008, 2021). "They identified that tumor-suppressive effects of miR-506 are associated with targeting SphK1 and inhibition of the SphK1/Akt/NF-κB signaling pathway." (PMID 35201458, 2021). "As an important regulator of lipid metabolism, SPHK1 (sphingosine kinase 1) plays a causal role in promoting malignant tumour biological properties through multiple pathways." (PMID 34857818, 2021). "As for S1PR4, a clinical study has shown that higher tumor expressions of SPHK1 and S1PR4 are associated with shorter disease-free survival and more advanced lymph node status in ER-negative breast cancer patients." (PMID 34820423, 2021). "In our study, HGSOC correlated with suboptimal tumor surgery and, thus, worse survival; whereas, high SPHK1 expression was associated with optimal tumor debulking." (PMID 33660008, 2021). "They showed that SphK1-deficient T cells reduce differentiation to Tregs and inhibition of SphK1 improves the anti-tumor activity of T cells." (PMID 35201458, 2021). "In tumor cells there is evidence that hypoxia causes a rapid activation of SPHK1, preceding HIF-1α accumulation." (PMID 31379883, 2019). "High SPHK1 expression was significantly associated with larger tumor size, deeper depth of tumor invasion, lymph node metastasis, advanced TNM stage, high LC3B expression, and peritoneal recurrence." (PMID 30791228, 2019). "We have firstly shown that SphK1 deficient tumor cells exhibited an increase in apoptosis and senescence and a decrease in proliferation." (PMID 29643998, 2018). "Sphingosine kinase 1 (SK1) is a protooncogenic enzyme expressed in many human tumours and associated with chemoresistance and poor prognosis." (PMID 30043096, 2018). "SPHK1 inhibitors can also cause tumor cell cytotoxicity, such as dimethylsphingosine and safingol, which concluded phase I clinical trials." (PMID 29186783, 2017). "High IGF1R and SphK1 protein co-expression in tumor tissue was associated with improved OS specifically in ER-positive disease and stratified for anti-endocrine therapy." (PMID 29207959, 2017).
tumor (continued). "We have previously shown that the sphingosine kinase 2 selective inhibitor ABC294640 has broad anti-tumor activity, that its effects mimic SphK2 ablation, and that loss of SphK2 impacts tumor growth more profoundly than loss of SphK1." (PMID 27517489, 2016). "In fact, increased SphK1 expression was associated with tumor size, lower survival, recurrence and poor prognosis in HCC, astrocytoma, and breast cancer patients." (PMID 27800303, 2016). "SPHK1 is also up-regulated by low oxygen tension and increased levels of SPHK1 are found in many human solid tumors underlying its role in tumor neovascularization and angiogenesis." (PMID 27284992, 2016). "S1P is generated through Sphk-catalyzed phosphorylation of sphingosine, and the Sphk1/S1P pathway has been implicated in tumor progression." (PMID 27811358, 2016). "In clinical HNSCC samples, human SphK1 expression was significantly higher compared to normal mucosa, and this was positively associated with depth of tumor invasion, metastasis, and clinical failure." (PMID 25197261, 2014). "Growth factors, including EGF, are known to stimulate SphK1 in several cell types and their overexpression in tumor cells is often associated with worse prognosis." (PMID 25309325, 2014). "It is well-documented that SphK1 is a key player in tumor growth, but the mechanism underlying its influence on invasion and proliferation has not been fully elucidated." (PMID 24970177, 2013). "We next studied if the association between SPHK1 and the expression of genes associated with macrophage functions could be explained by the S1P-mediated migration of monocytes to the tumor." (PMID 38339325, 2024). "Moreover, SphK1 upregulation is associated with tumor size, invasion depth, lymph node metastasis, stage, and lymphovascular invasion." (PMID 35541904, 2022). "In addition, previous studies have already linked the high expression of SPHK1 with tumor progression and the poor survival of patients with NSCLC, but the molecular mechanism still needs further investigation." (PMID 36361531, 2022). "In addition, a positive association between SPHK1 expression and tumor size, tumor stage, and histological differentiation was reported." (PMID 35681679, 2022). "Together, our review might provide insight into the close association between SPHK1 and pyroptosis and contribute to tumor treatment’s potential strategy." (PMID 33123153, 2020). "The miR-515-5P, a tumour suppressor shows to reduce SphK1 activity and loss of miR-515-5P." (PMID 31752564, 2020). "Moreover, an increase in the expression of sphingosine kinase (SPHK1), an enzyme that transforms sphingosine into S1P, causes the accumulation of S1P in the cell, thus promoting carcinogenesis and tumor formation." (PMID 31187044, 2019). "SphK1 expression knockdown in colorectal adenocarcinoma cell lines was associated with a decrease in tumor cell migration and invasiveness, probably due to interference with epithelial-mesenchymal transition (EMT), a process observed during cancer progression and spread." (PMID 30684960, 2019). "In addition, SphK1 expression is significantly associated with tumor size, tumor stag,e and histological differentiation." (PMID 29510489, 2018). "Here, we show that SPHK1 is tightly associated with tumor growth and apoptosis." (PMID 27811359, 2016). "While the importance of SphK2 in HNSCC is unknown, SphK1 has been implicated in tumor growth and cell transformation in HNSCC." (PMID 24970177, 2013). "Furthermore, we conducted integrated analyses to evaluate the relationship between SPHK1 expression and key immunological features, including immune cell infiltration, tumor mutation burden (TMB), microsatellite instability (MSI), and immune checkpoint gene expression." (PMID 41547931, 2026). "S1PR3 antagonism or knockdown was shown to reduce tumour size, whereas SPHK1 overexpression exacerbated tumour growth." (PMID 41253780, 2025).